EGF (epidermal growth factor)
Diseases named in the same sentence as EGF in open-access papers (continued):
Sharing a sentence is not in itself a finding about the gene and the disease.
bladder cancer (continued). "The effect of EGF and gefitinib on two EGFR-positive human bladder cancer cell lines has been investigated using array-based gene expression profiling." (PMID 17311025, 2007). "Since limited information exists concerning the expression of other parts of the EGF system, we examined the expression of the receptors HER3 and HER4 and their activating ligands, the heregulins (HRGs), in bladder cancer patients." (PMID 15583696, 2004). "In growth factor signaling, EGF-induced activation of HER2 triggers SHCBP1 phosphorylation at Ser273, which is essential for its subsequent nuclear import and for the activation of downstream targets including PLK1 in gastric and bladder cancer cells." (PMID 41009347, 2025). "The strong responsiveness of MMP1 to EGF relies on STAT3 phosphorylation and its interaction with c-JUN, and with this crucial activation of STAT3, T24 cells exhibit malignant characteristics in bladder cancer." (PMID 38320998, 2024). "EGFR was phosphorylated in bladder cancer cells by the EC-secreted EGFR ligands and EGFR ligands, including epidermal growth factor (EGF), amphiregulin, epiregulin, betacellulin, tumor necrosis factor-α and epithelial mitogen are upregulated in EC by co-culturing." (PMID 38602556, 2024). "Collectively, we demonstrate that the EGF-SHCBP1-RACGAP1-RAC1 axis acts as a novel regulatory mechanism of bladder cancer progression, which offers a new clinical therapeutic strategy to combat bladder cancer." (PMID 35013128, 2022). "First, we found that EGF did not increase the total expression of SHCBP1 protein but increased SHCBP1 expression in the nuclei of three bladder cancer cell lines, as revealed by immunoblotting and IF." (PMID 35013128, 2022). "In AR-positive bladder cancer cells, DHT could activate the epidermal growth factor receptor (EGFR)/ERBB2/ERK pathway in the presence of the epidermal growth factor (EGF)." (PMID 33919565, 2021). "Therefore, four overlapping genes (EGF, EGFR, VEGFA, and THBS1) were extracted from the bladder cancer and PI3K–AKT pathways." (PMID 30868054, 2019). "Because PDGFRB/EGFR heterodimers were reported to express on bladder cancer cells, and the EGF/EGFR pathway played an important role in bladder cancer development, PDGFRB was selected for further validation as a candidate biomarker of bladder cancer." (PMID 24801713, 2014). "In this study, EGF elevated the phosphorylation of cofilin without altering its expression level and induced the migration of T24 bladder cancer cells." (PMID 23374291, 2013). "We then performed the MTT assay to investigate the effects of EGF androgen and antiandrogen on cell proliferation of bladder cancer lines with vs. without AR (i.e., UMUC3-control-shRNA vs. UMUC3-AR-shRNA, 5637-AR vs. 5637-V and J82-AR vs. J82-V)." (PMID 22922989, 2012). "Thus, our results support the possibility that EGF mediates AR transcriptional activity through the EGFR and AR pathways in bladder cancer cells." (PMID 22922989, 2012). "Repeatedly, the AR expression increased by androgen with or without EGF in bladder cancer cells was abolished by an AR antagonist." (PMID 22922989, 2012). "EGF treatment induced Y40 phosphorylation, suggesting that ETK is active in bladder cancer cells." (PMID 21408190, 2011). "There was, in addition, a difference in mean EGF levels from 'normal' bladder samples from non-tumour bearing areas of bladder in patients with bladder cancer compared with 'normal' bladder tissue obtained at the time of organ retrieval surgery." (PMID 8605103, 1996). "Growth factors have been extensively researched in cancers, including bladder cancer, because of their role in cancer biology and clinical relevance as prognostic and therapeutic targets, and EGFR is a well-characterized initiator of the RAS signaling pathway upon activation by EGF." (PMID 36072391, 2022).
bladder cancer (continued). "Given that ISO could reduce cell viability in T24T bladder cancer cells with an approximate IC50 of 55 μM, we thus treated mouse epidermal Cl41 cells with ISO in concentrations of 30, 40, and 50 μM with exposure to TPA/EGF." (PMID 24797581, 2014). "EGF could also induce AR-positive bladder cancer cell proliferation in the absence of androgens." (PMID 28241422, 2017). "Growth factors (EGF and bFGF) and stimuli (PMA and LPA) that activated downstream oncogenic signaling (such as PKC, MEK/Erk and PI3K/Akt) could elevate the expression of KLF5, then increased VEGFA transcriptional efficiency and promoted bladder cancer angiogenesis." (PMID 26544730, 2015). "In contrast to insulin-induced AREG mRNA expression in RT4 bladder cancer cells, PI3K inhibition increased EGF-induced AREG mRNA expression, but not protein secretion." (PMID 27669890, 2016).
epidermoid carcinoma (65 papers, 1991 to 2026). "Although currently untargetable, FAT1 mutations have been implicated in resistance to epidermal growth factor inhibitors in squamous cell carcinomas." (PMID 41296436, 2025). "Acting by inhibiting EGF-induced receptor autophosphorylation and associated downstream anabolic pathways, anti-EGF nanobodies Ia1, L2–3.40 and IIIa3 completely blocked EGF-induced proliferation of squamous cell carcinoma cells in vitro." (PMID 34769339, 2021). "Most head and neck cancers (HNCs), specifically squamous cell carcinoma, express epidermal growth factor and are associated with an inadequate response to radiotherapy and chemotherapy." (PMID 32426197, 2020). "More than 95% of HNCs, especially squamous cell carcinoma, express epidermal growth factor, and are associated with a poor response to radiotherapy and chemotherapy." (PMID 32426197, 2020). "In contrast, other investigators have suggested that c-Jun interacts with the CRE of the prostaglandin endoperoxide synthase-2 promoter in epidermal growth factor-treated human epidermoid carcinoma cells." (PMID 40871473, 2025). "We found previously that human peripheral blood and EGF can modulate the activities of EGFR-specific drugs on inhibiting clonogenity in model EGFR-positive A431 squamous carcinoma cells." (PMID 37626832, 2023). "We showed that EGF abrogates the growth of squamous carcinoma A431 cells at concentrations exceeding 0.8 ng/mL with IC50 at ~0.4 ng/mL." (PMID 37626832, 2023). "EGF fusion proteins produced in the cytosol of E. coli have been shown to target human squamous carcinoma-derived A431 cells expressing high levels of EGFR." (PMID 35624572, 2022). "Two trials included patients who had epidermal growth factor sensitive mutations (CTRI/2015/08/006113 and CTRI/2016/08/007149) and the other two included squamous cell carcinoma (CTRI/2013/02/003422) and adenocarcinoma patients (CTRI/2014/08/00484)." (PMID 36072229, 2022). "The 5-year survival rate was high in patients with adenocarcinoma or squamous cell carcinomas with serum EGF concentration above 870 pg/ml, confirming sensitivity of the tumors to the EGF depletion." (PMID 34211836, 2021). "Dynamic patterning of epidermal growth factor (EGF) was shown to influence distribution of A431 squamous carcinoma cells across the gel and temporally control EGF internalization on the subcellular level." (PMID 32996270, 2021). "EGF-induced NF-κB activation was observed in A431 cells, an epidermoid carcinoma cell line expressing high levels of EGFR." (PMID 34769306, 2021). "The coiled-coil domain-containing 50 (CCDC50) protein (also termed Ymer) was identified as a phosphotyrosine-dependent signalling protein in epidermal growth factor (EGF)-stimulated human epidermoid carcinoma cells." (PMID 33277610, 2020). "PCI of rGel-EGF was highly effective against EGFR-expressing squamous cell carcinoma cells (SCC-026 and A-413) and even against cell lines resistant to the EGFR inhibitor cetuximab." (PMID 31936595, 2020). "PCI of EGF-Gelonin resulted in inhibitory effects on squamous cell carcinoma in a mouse xenograft model and reduction of tumor perfusion and necrosis induction in head and neck squamous cell carcinoma tumors." (PMID 29023422, 2017). "If HeLa cells have about 3–4 × 105 receptor molecules on PM which become saturated at EGF concentration of about 4 nM, the human epidermoid carcinoma cell line A431 possesses about 2–3 × 106 EGFR per cell which become saturated at about 25–30 nM of EGF." (PMID 26716513, 2016). "In squamous cell carcinoma cells, increased EGF signaling and subsequent increased interleukin (IL)-1ß contributed to chemotherapeutic resistance." (PMID 25216514, 2014). "In the first, A431 human epidermoid carcinoma cells were stimulated by EGF, triggering H2O2 intracellular production that lead to PTP1B oxidation and inhibition, while in the second experiment, rat-1 cells were stimulated with PDGF inducing SHP-2 oxidation." (PMID 25325054, 2014).
epidermoid carcinoma (continued). "In our study, we found that the IL-1β gene and protein expression were induced by EGF in squamous cell carcinoma." (PMID 23383347, 2013). "Differential manipulation of IL-1β by EGF in squamous cell carcinomas can offer new methods for targeting IL-1 in cancer therapy." (PMID 23383347, 2013). "EGF also induced IL-1β gene expression in squamous carcinoma cells, such as SCC4, SCC25, TU183, and CA922." (PMID 23383347, 2013). "Based on the efficacy of cetuximab in squamous cell carcinomas from other primary sites, there appears to be clinical rationale for evaluation of anti-epidermal growth factor inhibitors in anal squamous cell carcinoma." (PMID 22619735, 2012). "Epidermal growth factor (EGF)-treatment of squamous cell carcinoma (SCC) cells provokes changes in the expression of lineage markers, morphological changes, and a higher invasive and metastatic potential." (PMID 22479362, 2012). "To explore how different ligand concentrations affect the activation of EGFR-dependent signaling pathways, we stimulated serum-starved A431 epidermoid carcinoma cells for five minutes with twelve concentrations of EGF, ranging from 250 pM to 32 nM." (PMID 21264347, 2011). "As shown in a study with squamous cell carcinoma, inhibition of EGF (epidermal growth factor) using antagonists led to an increase in DSP protein levels." (PMID 22132232, 2011). "In addition, Neu3 rapidly mobilizes to the ruffle cell membranes in squamous carcinoma A431 cells in the presence of EGF (epidermal growth factor)." (PMID 39128726, 2024). "Because it remains unclear if Blimp-1 can be regulated by other stimuli beyond EGF, here we further investigated multiple stimuli for their regulation of Blimp-1 expression in keratinocytes and squamous cell carcinoma (SCC)." (PMID 35185556, 2022). "Anti-EGF nanobodies have shown similar success in human squamous cell carcinoma." (PMID 34769339, 2021). "Finally, we show that the proliferation of A431 squamous carcinoma cells is inhibited by relatively low, physiological doses of EGF." (PMID 33748471, 2021). "PLSCR1 has also been reported to interact with EGFR in EGF-stimulated epidermoid carcinoma cells." (PMID 32292520, 2020). "Additionally, EGF addition to human epidermoid carcinoma A431 cells, which highly express the EGFR, resulted in increased levels of intracellular ROS36." (PMID 32661331, 2020). "The MNT containing EGF as its ligand module and carrying 125I (labeled by N-succinimidyl-4-guanidinomethyl- 3-[125I]iodobenzoate) accumulated in the nuclei of human epidermoid carcinoma A431 cells very efficiently: 60% of the radioactivity entering the cells appeared in the nuclei." (PMID 30210340, 2018). "To examine whether derivative 3 could reduce the Ca2+ mobilization in the cell cytosol, we examined the response of squamous carcinoma A431 cells by adding epidermal growth factor (EGF) following pre-treatment with derivative 3 at 25 and 50 μM." (PMID 26966420, 2016). "Therefore we used the EGF stimulated human squamous carcinoma cell line A431 with a high expression of EGFR." (PMID 27322232, 2016). "Therefore, the lack of increase in expression of α2/β1 integrin, and the de-adhesion response, are features that distinguish the EGF-induced adhesion effects in Capan-1 cells from that in squamous carcinoma cells." (PMID 15801978, 2005). "Bafilomycin A1, a macrolide antibiotic that has been demonstrated to inhibit vacuolar type H+-ATPase, inhibits endosomal and lysosomal acidification and blocks lysosomal degradation of EGF in A431 cells (human epidermoid carcinoma cells), blocked degradation of 125I-EGF in KB-3-1 cells." (PMID 12698203, 2003). "We investigated the effect of EGF on the growth of an EGF receptor-hyperproducing human epidermoid carcinoma, A431 tumour, and on a human small-cell lung carcinoma, H69 tumour, without detectable EGF receptor by using sialoadenectomised (sialex) mice as an endogenous EGF-suppressed animal model." (PMID 7547232, 1995).
epidermoid carcinoma (continued). "However, EGFR could also be additionally activated by other mechanisms, such as oxidation in an EGF-dependent manner in squamous carcinoma cells." (PMID 28122935, 2017). "We used the human epidermoid carcinoma cell line A431, which expresses high levels of the EGFR and is a representative cell line for research on EGF-stimulated macropinocytosis." (PMID 35428847, 2022). "Lung cancer, colorectal cancer, EGFR, HER-targeted therapy, human blood serum, cetuximab, erlotinib, trastuzumab, EGF, neuregulin, NRG, TGF-alpha, squamous cell carcinoma, A431, drug resistance." (PMID 33748471, 2021). "We used the human vulva epidermoid carcinoma cell line A431 because these cells express high levels of wild-type EGFR and respond strongly to EGF stimulation." (PMID 32053105, 2020). "Previously, we performed proteomic analysis of tyrosine phosphorylation using the epidermal growth factor (EGF)-treated A431 cell line, which highly expresses EGF receptor (EGFR) in human epidermoid carcinoma." (PMID 31718706, 2019). "The antiproliferative activity of these hybrids was evaluated on immortalized human keratinocyte (HaCaT) cells stimulated with epidermal growth factor (EGF), an actinic keratosis (AK) model, and on human squamous cell carcinoma (SCC) cells (A431)." (PMID 31075867, 2019). "The addition of epidermal growth factor (EGF) to serum-free and serum-containing cell culture media results in a marked inhibition of cell proliferation in the A431 human epidermoid carcinoma cell line." (PMID 28417908, 2017). "When A431 cells (human epidermoid carcinoma, high expressor of EGFR) were treated with GFP-tagged exosomes (20 μg/mL) for 24 h at 37 °C, addition of the EGF (500 nM) significantly increased cellular uptake of the exosomes by approximately 27-fold." (PMID 29023422, 2017). "For example, IKKα can bind and repress the promoter of epidermal growth factor (EGF), among others, thus suppressing the EGF receptor/Ras/ERK pathway to prevent squamous cell carcinoma (SCC)." (PMID 28587092, 2017). "Reverse-transcription PCR; western blotting; ELISA and luciferase assays were used to test the effect of compound 1 on EGF-stimulated expressions of COX-2 and IL-8 in A431 human epidermoid carcinoma cells." (PMID 23774942, 2013). "Given that Blimp-1 is involved in skin biology and can be induced by EGF and PMA in human keratinocytes, we were interested to further explore the regulation and function of Blimp-1 in keratinocytes and squamous cell carcinoma (SCC)." (PMID 35185556, 2022). "In order to test if the function of CHP-1 in the EGFR signaling pathway is conserved in mammals, we inactivated the CHP-1 homolog CHORDC1 in human A431 epidermoid carcinoma cells, which express high levels of the wild-type EGFR and undergo a phenotypic switch in response to EGF stimulation." (PMID 32053105, 2020). "We first performed far-Western blotting, a reverse-phase SH2 binding assay to quantify changes in the binding sites for multiple SH2 domains across the set of phosphoproteins in EGF-stimulated A431 cells, an EGFR-overexpressing squamous-cell carcinoma cell line." (PMID 27071344, 2016). "In EGF-treated A-431 cells, an epidermoid carcinoma cell line overexpressing wtEGFR, Nimotuzumab did not induce activation of AKT and rapamycin treatment marginally reduces pAKT levels." (PMID 25886314, 2015). "ABL anti-tumor effect in BT-549 cells and Src-transformed fibroblasts was not dependent on EGF secretion, as recently reported in neck and squamous carcinoma cells." (PMID 25803821, 2015). "Another study has demonstrated that EMT was induced by EGF in squamous cell carcinomas of the head and neck without changes in E-cadherin expression." (PMID 23631593, 2013).
epidermoid carcinoma (continued). "Using quiescent HaCaT keratinocytes, tumorigenic A431 epidermoid carcinoma cells, primary bronchial epithelial explants, and vocal fold carcinoma (VFC) cells, we find that flocking induction depends on transcriptional programs activated downstream of epidermal growth factor (EGF)." (PMID 41431893, 2025). "The EGFR in A431 cells, the squamous cell carcinoma cell lines, are glycosylated by A antigen, as well as Lewis Y antigen, another product of FUT1 that is mostly expressed in cancer cells, and these sugar structures influence the binding of the EGF to its binding site on the receptor." (PMID 39420441, 2024). "We found that squamous carcinoma A431 cells could not form colonies at EGF concentrations exceeding 0.5 ng/ml." (PMID 33748471, 2021). "We first examined the EGF-induced endocytic degradation of EGFR in a panel of NSCLC cell lines, which includes all major histologic subtypes: adenocarcinoma (A549, H1299, HCC827, H1650, and H1975), large cell carcinoma (H460), and squamous cell carcinoma (H226 and SK-MES-1)." (PMID 29976202, 2018). "Thus, EGF, rather than TGFβ is a key factor in malignant progression of squamous cell carcinoma lines." (PMID 22479362, 2012). "However, in squamous carcinoma A431 cells, which express high levels of endogenous EGFR, EGF at pM range stimulates cell growth, while at nM range inhibits proliferation, arrests cell cycle, alters cdk2 activity by induction of p21, and even induces cell apoptosis." (PMID 22927910, 2012). "A similar inhibition of EGF internalization and EGFR phosphorylation has been reported for polychlorinated biphenyls (PCB-126 and PCB-153) and trans-nonachlor in a human epidermoid carcinoma cell line." (PMID 35054855, 2022).